BCL2 (BCL2 apoptosis regulator)
Diseases named in the same sentence as BCL2 in open-access papers (continued):
Sharing a sentence is not in itself a finding about the gene and the disease.
cancer (continued). "It was reported that changes in the balance of Bcl-2/Bax that directly control the permeability of mitochondria are involved in the differential induction of apoptosis in cancer versus normal cells." (PMID 32235536, 2020). "The elevated concentrations of anti-apoptotic BCL-2 proteins in cancer cells protect the cancer cells from apoptosis, prolonging their lifespan." (PMID 32645956, 2020). "Specifically, ALKBH5 suppresses the BCL-2 expression, which was demonstrated to inhibit autophagy in cancer." (PMID 32258108, 2020). "In fact, BH3 mimetics are emerging as promising avenues against cancer, particularly in OC, where BCL2 inhibition has proven to sensitize OC cells to DNA damage agents." (PMID 32268485, 2020). "Previous studies have identified the role of Sch B in inducing cell apoptosis through caspase activation and BCL-2 inhibition in different cancer cells." (PMID 32635653, 2020). "Taken together, these results demonstrate that the combination of T3 and the Bcl-xL/Bcl-2 inhibitor promoted the death of cancer cells." (PMID 33064779, 2020). "Although the 10 μM concentration is high compared with the concentration of venetoclax used as a BCL-2 inhibitor, based on previous publications, this concentration is common among targeting cancer treatment drugs as reversal agents." (PMID 32085398, 2020). "After 100 days of exposure, there appeared to be a significantly higher overexpression of cancer-related cytokines Tnf and Il6, anti-apoptotic Bcl2, NF-κB factor Rela, and oncogenic factor Egfr compared to the 45-day exposure." (PMID 32344873, 2020). "Silencing of Bcl-2 using siRNA induces apoptosis in cancer cells and diminishes their proliferation." (PMID 32784981, 2020). "BCL2 is an important therapeutic target in hematological malignancies because it drives resistance to apoptosis and is a key feature of cancer cells that sustains tumor growth and resistance to treatment." (PMID 33067577, 2020). "Following NF-κB inhibition, the cancer-related genes like Bcl-2, Bcl-xL, cyclin D1, IL-6, COX-2 and MMP9 are subsequently downregulated." (PMID 32131560, 2020). "BET inhibitor, as an epigenetic regulator inhibitor, reduces the expression of oncogenes such as Myc and Bcl-2, which affects cancer growth and development." (PMID 33412753, 2020). "BH3 mimetics are a novel class of anti-cancer drugs that mimic the action of certain BH3-only anti-apoptotic proteins of the B-cell CLL/lymphoma 2 (BCL2) family, which directly initiate apoptosis, downstream of many common oncogenes." (PMID 32764384, 2020). "The anti-apoptotic functions of NF-κB, Bcl-2, and Bcl-XL play an important role in the development of resistance to cancer therapy." (PMID 33680921, 2020). "The SF3B1 inhibitor E7107 in combination with Bcl-xL/Bcl-2 inhibitors enhances cytotoxicity to cancer cells based on the evidence that E7107 alters splicing of MCL1, but not that of BCL2L1." (PMID 33064779, 2020). "During the experiment, the expression of the proapoptotic BAX gene and antiapoptotic BCL2 gene in ovarian OV7 cancer cells treated with CAPE were evaluated." (PMID 32752091, 2020). "Yet, such cancer cells often are highly dependent on Bcl-2 for their survival, a feature that is exploited by so-called BH3-mimetic drugs." (PMID 32708132, 2020). "In the meantime, western blot analysis revealed an increased ratio of Bax/Bcl-2 in the cancer cells treated with GA." (PMID 32913452, 2020). "Venetoclax belongs to BCL2 homology 3 (BH3) mimetics that trigger cancer cell apoptosis by displacing proapoptotic BCL2 proteins, including BIM from the anti-apoptotic BCL2 protein." (PMID 32197371, 2020).
cancer (continued). "As a result, the comprehension of the interaction of BH3-only proteins with other BCL-2 members acting as apoptosis activators resulted in the development of BH3-only mimetic molecules as a strategy to cancer therapy." (PMID 32309275, 2020). "The activated PI3K/AKT/mTOR pathway can decrease the BCL-2 homology domain (BH3) mimetic effectiveness in cancer cells by upregulating anti-apoptotic BCL-2 family members, such as myeloid cell leukemia-1 (MCL-1) and B-cell lymphoma-extra large (BCL-XL)." (PMID 32131492, 2020). "This prevents the sequestration of pro-apoptotic Bcl-2 family proteins, often upregulated due to oncogenic stress and tips cancer cells “addicted” to Bcl-2 for survival over the edge of apoptosis." (PMID 32708132, 2020). "Senescent cells, like cancer cells, are resistant to apoptosis through the upregulation of BCL-2 anti-apoptotic proteins." (PMID 32295081, 2020). "The Akt/mTOR signaling pathway is typically abnormally activated in a variety of malignant tumors and causes abnormal expression of downstream genes such as PFKFB2, p21, Vimentin, and Bcl-2." (PMID 33282634, 2020). "MiR-181a has been shown to promote apoptosis by increasing Fox01 acetylation and by repressing BCL-2 in cancer cells." (PMID 33348707, 2020). "The results demonstrated that exosiBcl-2 (siRNA against bcl-2-loaded exosomes) inhibits bcl-2 expression followed by an increase in apoptosis and a decrease in cell growth, migration, and invasion of cancer cells in vitro." (PMID 33023062, 2020). "One of the main factors involved in this process are proteins belonging to the B-cell lymphoma 2 (Bcl-2) family, and the imbalance between pro-apoptotic and anti-apoptotic members of this family contributes to the development of cancer." (PMID 32260403, 2020). "The promise of personalized biomarker technology and rational combinations of BCL-2 inhibitors with other branches of cancer therapy are imminent, and will certainly add to our therapeutic arsenal to improve outcomes in a wider group of patients." (PMID 32131385, 2020). "Another explanation can be deduced from the fact that Apoptin on interaction with Bcl-2 and Akt completely hijacks their function and reverses their role as pro-survival factors in cancer cells." (PMID 32671070, 2020). "Identification of the important role of BCL2 in cancer development and chemo resistance, rendered it as an ideal target for cancer therapeutics." (PMID 32938954, 2020). "Taken together the underlying mechanisms for the observed markedly promoted growth inhibition and apoptosis induction by combined therapy can be the concomitant suppression of CDK1, CDK9, c-FIP, Mcl-1 and Bcl-2 and upregulation of Bax in cancer cells." (PMID 32375399, 2020). "Induction of apoptosis in cancer cells by C5 was inversely related to the level of Bcl-2 expression." (PMID 32075108, 2020). "The cancer cell lines that were weakly affected by C5 had high Bcl-2 expression levels and those that were strongly affected by C5 had low Bcl-2 expression levels." (PMID 32075108, 2020). "Morusin-mediated inhibition of the NF-κB pathway also leads to reduced expression of Bcl-2 and upregulation of pro-apoptotic proteins including Bax and caspase-3, which results in the apoptotic death of the cancer cells." (PMID 32906784, 2020). "The mRNA expression level of Bcl-2 was up-regulated in cisplatin-resistant cancer cells, but its P-value, which was < 0.05, was only significant in the differential expression of A2780DDP and A2780 cells." (PMID 33585454, 2020). "Increased Bax/Bcl-2 ratio up-regulates caspase-3 activity and subsequently triggers programmed cell death in cancer cells." (PMID 33375383, 2020). "Mechanistically, tambulin downregulates HDAC1, which in turn regulates the Bcl-2/caspase signaling pathway and promotes cancer cell apoptosis." (PMID 32903420, 2020).
cancer (continued). "According to multiple lines of evidence indicated, MCL1 is commonly up-regulated in various cancers and is considered as a primary factor to resistance the treatment with the BCL2 inhibitor." (PMID 33126914, 2020). "Much of the published data on this cluster indicate that miR-15/16 members directly target the apoptosis regulator Bcl-2 to inhibit cellular proliferation, induce cancer cell apoptosis, and thereby reduce tumorigenicity." (PMID 32477070, 2020). "Additional effects of Bcl-2 inhibitors on cancer cells beyond their role in triggering apoptosis have been demonstrated, including the induction of cell cycle arrest, the inhibition of cell proliferation and the induction of autophagy and necrotic cell death." (PMID 32367199, 2020). "Certainly, emerging attempts to target BCL-2 antiapoptotic members will benefit the treatment of cancer." (PMID 32699213, 2020). "In treated rat carcinomas, we found significant caspase-3, Bax, and Bax/Bcl-2 expression increases; on the other side, a significant down-regulation of Bcl-2, Ki67, CD24, ALDH1, and EpCam expressions and MDA levels." (PMID 33375383, 2020). "The over-expression of anti-apoptotic Bcl-2 and the reduced expression of pro-apoptotic Bax is common in many human cancers." (PMID 31771152, 2019). "Bcl-2 is widely known for its anti-apoptotic function, and the repression of Bcl-2 expression is an available method for cancer therapy." (PMID 31889894, 2019). "Chemotherapy-resistant cancer cells are characterized by the overexpression of members of the anti-apoptotic B-cell lymphoma 2 (Bcl-2) protein family, such as Bcl-XL, Bcl-2, and Mcl-1." (PMID 31798573, 2019). "Bcl-2 is an antiapoptotic protein that can regulate the activation of the cellular apoptotic pathway and overexpression in many cancer." (PMID 30842340, 2019). "BCL-2 inhibitors have been approved for their use as an anti-cancer drug by the U.S. Food and Drug Administration (FDA) as the first agent among all intrinsic apoptosis inhibitors." (PMID 31370269, 2019). "The impressive selectivity and efficacy of BH3 mimetics for treating cancer has largely been limited to BCL-2 dependent hematological malignancies." (PMID 30185825, 2019). "Substantial evidence reveals that the potential mechanisms between autophagy and apoptosis including endoplasmic reticulum stress, PI3K/mTOR, and Bcl-2 in cancer cells." (PMID 31817161, 2019). "BCL-2 protein is considered as an imperative target for the treatment of cancer due to their significant involvement in cell survival and death." (PMID 31450709, 2019). "We also examined expression of several signaling molecules whose expression has been associated with chemo-resistance in other cancer types, such as ABCG2, c-FLIP, BCL2." (PMID 30382189, 2019). "This agrees with studies in other cancers showing high BCL-2 levels predict better responses to ABT-19928." (PMID 31019203, 2019). "The gene expression ratio BAX/BCL-2 indicated the induction of mitochondrial apoptosis in cancer cell lines." (PMID 30642021, 2019). "Specific phytochemicals efficiently raise the Bax/Bcl-2 ratio and initiate the activation of caspase-3 in cancer cells in vitro." (PMID 30970626, 2019). "One of these, the pro-survival Bcl-2 subgroup, can enable cancer cells to escape cell death with impact on cancer development." (PMID 31825969, 2019).
cancer (continued). "These two small molecules were designed to mimic the action of the BH3-only proapoptotic proteins, binding with high affinity to anti-apoptotic Bcl-2 and Bcl-xL proteins to induce apoptosis of treated cancer cells." (PMID 31324803, 2019). "The well-known Bcl-2 inhibitory natural product (-)-gossypol, which has been used in cancer clinical trials, was used as a positive control." (PMID 30986908, 2019). "The BCL-2 (B-cell lymphoma 2) protein plays an anti-apoptotic role, leading to prolonged cancer cell survival." (PMID 31064156, 2019). "Our results indicate that cancer cells are addicted to Bcl-2 acting at the ER Ca2+ stores to regulate IP3R-mediated Ca2+ release." (PMID 29899382, 2019). "Several reports have been demonstrated that the Bcl-2 and Bcl-XL are widely over expressed in different forms of cancers." (PMID 31461995, 2019). "We then analyzed the levels of BCL-2, which is also one of the most important oncogenes involved in cancer for inhibiting apoptosis." (PMID 31695781, 2019). "Real-time PCR analysis did not reveal any significant differences in the mRNA levels of β2M, HER2, HIF-1α, VEGF, and Bcl-2 between the cancer tissues and adjacent tissues (p > 0.05)." (PMID 30866857, 2019). "In another way, transcriptionally or post-transcriptionally repressing the expression levels of anti-apoptotic BCL-2 members in cancer is also promising." (PMID 31683603, 2019). "At the same time, consistent overexpression and dysregulation were observed for BAX and Bcl-2, respectively, in all the cancer cells." (PMID 32010609, 2019). "Recent studies have identified Bcl-2 as a modulator of apoptosis, which has opened up novel therapeutic treatment strategies for cancer." (PMID 31319483, 2019). "Most (130/180, 72%) of the FMCs expressed Bcl-2, including 55% (99/180) in at least 10% of the neoplastic cells, and 17% (31/180) in at least 65% of the cancer cells, which was the threshold for positivity with prognostic significance." (PMID 30630524, 2019). "A carbazole-piperazine hybrid molecule ECPU-0001 was designed and synthesized as a potent BCL-2 targeting agent with effective anticancer cancer activity." (PMID 31450709, 2019). "As ABT-737 selectively targets certain anti-apoptotic proteins, a method called BH3 profiling was developed to detect and analyze cancer cells’ dependency on BCL-2 and to predict the sensitivity of ABT-737 in these cells." (PMID 31652776, 2019). "Although CLL is largely Bcl-2–dependent, other cancers use a combination of anti-apoptotic proteins to survive, requiring either multiple BH3-mimetics or ones with broader binding characteristics." (PMID 31681471, 2019). "Upregulation of the anti-apoptotic BCL-2 proteins and loss of pro-apoptotic BH3 proteins has been observed in many cancers." (PMID 31405035, 2019). "Taken together, these findings support the idea that dn-ATF5 promotes caspase-dependent apoptotic death of cancer cells and that it does so by multiple pro-apoptotic actions including downregulation of survivin and BCL2." (PMID 31551409, 2019). "Silencing of BCL-2 with the use of an antisense oligonucleotide appeared to be a promising cancer therapeutic approach." (PMID 31064156, 2019). "The clinical success of ABT-199 has shown that BH3 mimetics have the potential to be viable therapeutic options for cancers that depend on BCL2 for survival." (PMID 30796196, 2019). "Obatoclax mesylate is a further example of an indole-based pan-Bcl-2 inhibitor that has been studied in cancer clinical trials (e.g. leukaemia and lymphoma)." (PMID 30986908, 2019). "In summary, we here propose an integration of bioinformatics approaches, linking -omics data to structural ensembles, to unveil the pro-survival Bcl-2 signature in cancer." (PMID 31825969, 2019).
cancer (continued). "As an adjuvant therapy, co-administration of HSP90 inhibitor, NVP-AUY922, with ABT-737, BCL-2 inhibitor, enhances the anti-cancer effect of ABT-737 by targeting MCL-1 protein that grants the cancer resistance to ABT-737 in small cell lung cancer." (PMID 31878360, 2019). "This summary of the development of Bcl-2 inhibitors provides worthwhile viewpoints on the use of biomedical approaches in future cancer therapy." (PMID 31662966, 2019). "BCL2 has been well-established as a therapeutic target due to its important roles in apoptosis, and has a number of pharmaceutical initiatives in cancer treatment." (PMID 31450613, 2019). "Meanwhile, ginsenoside Rg5 can also reduce Bcl-2 protein and increase the expression of Bax protein in gastric cancer cells, thereby reducing the activity of cancer cells." (PMID 31636686, 2019). "Although overexpression of anti-apoptotic Bcl-2 proteins is seen in many cancers, by itself this is only weakly oncogenic, if at all." (PMID 31681471, 2019). "Anti-apoptotic proteins, Bcl-2 and Mcl-1 have been studied extensively, given their ability to induce chemo-resistance in different cancers, including AML." (PMID 31466259, 2019). "The pro-apoptotic (Bax) and anti-apoptotic (Bcl2) proteins are key proteins in the signaling pathway of cell apoptosis and are also used as a therapeutic target for cancer treatment via apoptotic pathway affection." (PMID 31244309, 2019). "MDA-MB-231 and HeLa are Bcl2-expressing cancer cell lines where Bcl-2 inhibitory molecules have shown protein down-regulation following treatment." (PMID 30986908, 2019). "We found that disrupting the Bcl-2/IP3R interaction with BIRD-2 switched Ca2+ signaling within cancer cells from pro-survival to pro-death, resulting in cancer cell death." (PMID 29899382, 2019). "The Bcl-2 family plays a key role in the regulation of this apoptotic pathway; for example, an increased Bax/Bcl-2 ratio up-regulates caspase-3 and increases apoptosis in cancer cells." (PMID 30970626, 2019). "The mechanism of how Yoda1 sensitizes cancer cells to TRAIL is potentially more complex than calpains reducing Bcl-2 activity." (PMID 31685811, 2019). "For instance, tetrocarcin A has been found to interfere with the Bcl2 pathway inducing apoptosis in cancer cells." (PMID 31010150, 2019). "The anti-apoptotic proteins of Bcl-2 family, such as Bcl-2, are overexpression in numerous tumors, and contribute to cancer formation, development, and therapy resistance." (PMID 31057406, 2019). "In this context, the research and development of Bcl-2 inhibitors is believed to have great potential for the discovery of novel pharmacological modulators in cancer." (PMID 31143550, 2019). "Several transcription factors, including NF-κB, are suggested to regulate the expression of Bcl-2 and Bcl-xL in several cancer types." (PMID 30857226, 2019). "Some of the quinoline-based oxadiazole analogues (e.g. compound 6i) were found to exhibit sub-micromolar anti-proliferative activity in Bcl-2-expressing cancer cell lines, and sub-micromolar IC50 activity within a Bcl2-Bim peptide ELISA assay." (PMID 30986908, 2019). "Several approaches have been made to downregulate the BCL2 expression in cancer cells toward cancer therapy, including using small molecules to disrupt protein–protein interactions, antisense oligonucleotides, and peptidomimetics." (PMID 30682877, 2019). "The suppression of bcl-2 and IL-6 by either pre- and post-application of inhibitor is especially important because of bcl-2 role in anti-apoptosis and IL-6 role as a cancer-related cytokine." (PMID 31164956, 2019). "Silencing of Bcl-2 by siRNA followed by treatment with etoposide or doxorubicin had reduced the number of viable cancer cells and sensitized them to drug-induced apoptosis." (PMID 31064156, 2019). "BCL2 overexpression is observed in many tumors, so this anti-apoptotic protein is now well established as a validated, high-value cancer target." (PMID 30961650, 2019).